Y_RNA (Y RNA )
Gene: Miscellaneous RNA gene on chromosome 1 (240,698,320 to 240,698,429, forward strand). Ensembl gene ENSG00000199241.
Homologues: Orthologues: chimpanzee Y_RNA (100% identical). Paralogues in human: RNY1 (87% identical), Y_RNA (85% identical), Y_RNA (84% identical), Y_RNA (83% identical), Y_RNA (82% identical), Y_RNA (81% identical), Y_RNA (80% identical), Y_RNA (79% identical), RNY1P11 (78% identical), RNY1P8 (78% identical), Y_RNA (78% identical), RNY1P12 (77% identical), and 94 more.